CD163 (CD163 molecule)
Diseases named in the same sentence as CD163 in open-access papers (continued):
Sharing a sentence is not in itself a finding about the gene and the disease.
breast carcinoma (continued). "In the present study, we demonstrated a similar pattern of CD8 + and the suppressor CD163 + cells among the different breast cancer subtypes." (PMID 38349444, 2024). "Meanwhile, inhibition of ApoE expression in THP-1 cells blocked the CD86 downregulation and the CD163 upregulation induced by breast cancer cells." (PMID 39695088, 2024). "In summary, this study revealed the heterogeneity among TAMs in breast cancers, as identified by CD163 and CD206." (PMID 38893266, 2024). "Collectively, CD163+ TAMs, especially those with FABP4 expression, are positively associated with tumor growth and metastasis in breast cancer patients." (PMID 39513934, 2024). "Recently, meta-analysis demonstrated that a high density of TAMs, especially CD163+ TAMs, predicted poor survival outcomes in breast cancer." (PMID 39513934, 2024). "This study compared the clinical significance of CD206 and CD163 TAMs in a series of well-characterized breast cancers." (PMID 38893266, 2024). "In breast cancer, CD163 + and CD206 + M2-like TAMs have been observed in very close proximity to αSMA + CAFs." (PMID 39068459, 2024). "In particular, the CD163 TAM-to-sTIL score was determined to be an independent feature in breast cancer survival." (PMID 38893266, 2024). "(C) Expression of FABP4 and CD163 was highly correlated as analyzed by the Spearman correlation analysis in breast cancer tissues." (PMID 39513934, 2024). "Another study assessed the prognostic impact of CD163 in 398 breast cancer patients and came to a different conclusion, demonstrating that high CD163 + cell count is associated with improved OS in TNBC but not in luminal tumors." (PMID 38349444, 2024). "In this study investigating 278 early breast cancer cases with a long follow-up period (median 13.1 years), a high CD163+ TAM count represented a strong independent factor for a poor prognosis." (PMID 38339385, 2024). "The preclinical result of emactuzumab, a CSF1R antibody, established its efficacy in targeting the CD163+ TAM population in breast cancer." (PMID 38715072, 2024). "(A) Comparison of H&E and CD163 staining (brown) between an example of small and large breast cancer tumors in breast cancer patients." (PMID 39513934, 2024). "The spatial distribution of CD163 TAMs and their interactions with tumor-infiltrating lymphocytes (TILs) refined the prognostic value in breast cancer." (PMID 38893266, 2024). "Macrophage colony-stimulating factor (M-CSF), TGF-β, and vascular endothelial growth factor (VEGF) from primary tumor supernatants of breast cancer-induced healthy donor blood monocytes to differentiate into CD163-high CD86-low IL-10-high M2-like macrophages." (PMID 39199574, 2024). "CD163 has dethroned the earlier considered pan-macrophage marker CD68 as a better predictor for poor survival of breast cancer patients." (PMID 39451197, 2024). "We also observed the presence of Ki-67+ CD163+ TAMs in tumours from patients with primary and metastatic breast cancer and lung cancer, suggesting proliferating TAMs contribute to the accumulation of TAMs in many cancer types." (PMID 38903497, 2024). "In the same study, conditioned media from the MDA-MB231 breast cancer cell line induced macrophage differentiation into CD163+ TAMs in vitro via cancer cell secreted CSF-1." (PMID 39044824, 2024). "The expression of pro-tumorigenic macrophage marker CD163 was decreased in macrophages treated with a conditioned medium (CM) from HSP70-silenced breast cancer cells." (PMID 36980788, 2023). "We found that PTPN1 expression is associated with the extent of immune infiltration of CD163+ M2-like TAMs and CD8+ T cells and the expression of the immune checkpoint protein, PD-L1, in breast cancer." (PMID 37936713, 2023). "In breast cancer CD163+ CD14lowCD16+ and CD163+ CD14+CD16+ monocytes were indicative for the presence of the malignancy, and CD14lowCD16+HLA-DR + monocytes were predictive for the good response to neoadjuvant chemotherapy." (PMID 37628978, 2023).
breast carcinoma (continued). "Apart from our finding of an expression correlation between CD155 and macrophages, CD155 related to CD68/CD163 was also observed in breast cancer tissues." (PMID 37441080, 2023). "Descriptions of CD163-positive cancer cells have been reported for several solid cancers, including breast cancer and colorectal cancer." (PMID 37190178, 2023). "further found that the densities of CD8+ and CD163+ cells were different in the TC and IM, and the combined evaluation of both compartments was significantly related to breast cancer survival." (PMID 37090736, 2023). "These initial investigations of CD163+ TAMs in breast cancer have largely depended on research-focused pathologists to visually enumerate the cells, which is both laborious and subjective, and impedes implementation of these analyses into clinical practice." (PMID 35053472, 2022). "Most TAMs have M2-like phenotype (CD163) and breast cancer cells can secrete factors to promote macrophage differentiation toward the M2-like phenotype." (PMID 34983451, 2022). "In macrophages cocultured with Adam17–/– 4T1 or E0771 breast cancer cells, we found significantly lower expression of CD163 and/or CD206 in at least 1 of 2 Adam17–/– clones, as compared with macrophages cocultured with WT cancer cells." (PMID 35998057, 2022). "While most FDA-approved immunotherapies target CD8+ cytotoxic T cells, the role of CD4+ helper T cells and CD163+ macrophages is less well defined but increasingly seen as key players in the breast cancer microenvironment." (PMID 36376974, 2022). "In this report, we have shown a direct correlation between densities of CD8+ cells with densities of CD163+ and FoxP3+ cells in the primary tumors of patients with breast cancer." (PMID 36551693, 2022). "The expression of CD163, a highly specific marker of M2-like macrophages, was evaluated by immunohistochemistry in 105 human breast cancer tissue samples." (PMID 35715860, 2022). "There is a great need for objective, machine-based approaches to effectively capture the information value that can be provided by the density and spatial proximity of CD163+ TAMs in breast cancer." (PMID 35053472, 2022). "The accumulation of CD163+ macrophages intratumorally in dense frequencies is an unfavorable prognosticator in many types of cancer, including breast cancer." (PMID 36551693, 2022). "Though analyzing the expression of circWWC3, IL-4, PD-L1, and CD163 in 140 cases of breast cancer tissues, we found that high expression of circWWC3 was associated with poor overall survival and disease-free survival of breast cancer patients." (PMID 35996149, 2022). "The basal-like subtype expressed significantly higher levels of CD163 mRNA than luminal and Her2-positive breast cancer subtypes." (PMID 35715860, 2022). "The aim of our study was to evaluate the potential prognostic value of the prevalence and the spatial localization of CD163+ TAMs in tumor tissue from breast cancer patients treated with chemotherapy after surgery." (PMID 35053472, 2022). "On the other hand, the presence of M2-like macrophages, or high expression of CD163 marker in TNBC and basal-like breast cancer has been associated with a more aggressive cancer phenotype and poor survival." (PMID 36531051, 2022). "Subsequently, the mRNA expression of CD163 was analyzed using publicly available TCGA datasets for breast cancer." (PMID 35715860, 2022). "Overall, at least two molecular mechanism for tumor-supporting function of CD163+ TAMs were identified to date: inhibition of tumor suppressor TAp73 in breast cancer and activation of STAT3 signaling in TAMs and in r fibrosarcoma cells." (PMID 36686729, 2022). "Our results demonstrate for the first time that close spatial proximity of CD163+ TAMs to cancer cells and the average number of adjacent or communicating CD163+ TAMs are independent predictors of unfavorable prognosis in breast cancer." (PMID 35053472, 2022).
breast carcinoma (continued). "Although we focused on the analysis of breast cancer data, higher CD163+ TAM density has been shown to be correlated with worse prognosis in other cancer subtypes such as cutaneous melanoma, colorectal carcinoma, and ovarian carcinoma." (PMID 35053472, 2022). "To demonstrate its clinical relevance, we assessed the correlation between PYK2 expression (PTK2B gene) and macrophage markers (CD68, CD163) in human breast cancer datasets." (PMID 35092356, 2022). "Expression of the M2-like macrophage marker CD163 was evaluated by immunohistochemistry in human breast cancer tissues." (PMID 35715860, 2022). "Our data, while preliminary, would support combined regimens of immunotherapy or chemotherapy with the addition of FoxP3+ and CD163+ macrophage-targeting agents in breast cancer." (PMID 36551693, 2022). "In this study, we demonstrate that high frequencies of CD163+ and FoxP3+ cells in the tumors of patients with breast cancer co-exist with CD8+ cells only when the latter are also in dense frequencies." (PMID 36551693, 2022). "The IHC data revealed that the ZEB1 and DNMT1 expression levels were much higher in breast cancer tissues with high CD163 expression." (PMID 36273188, 2022). "Our own previous results on breast cancer (BC) patients revealed that the percentage of CD163-expressing CD14-CD16+ and CD14+CD16+ monocyte subpopulations was higher in BC patients compared to healthy women." (PMID 36733385, 2022). "Studies in early breast cancer patients have shown that high numbers of CD163+ M2-macrophages significantly correlate with short RFS and OS rates." (PMID 36551522, 2022). "In this study, we found the evidence that CD163 is elevated on the circulating monocytes in patients with breast cancer and is intensively recruited to the tumor site, suggesting that CD163 can be used as a marker for monocyte-derived TAMs." (PMID 35237501, 2021). "The concentrations of soluble CD163, a marker of macrophages M2 and galectin 3 (Gal3), rather related to M1 macrophages, in the plasma of healthy controls and breast cancer patients were also determined." (PMID 33916440, 2021). "Recent studies have shown that high expression of CD163 is related to a poor prognosis in breast cancer and glioma patients." (PMID 34195091, 2021). "In any case, Shabo and colleagues detected the expression of macrophage antigens DAP12, MAC387, and CD163 in human breast cancer and colorectal cancer tissues." (PMID 34503305, 2021). "The scavenger receptor CD163 has also been used to identify some TAM populations and has been shown to associate with early recurrence and reduced survival in breast cancer patients." (PMID 33968034, 2021). "In breast cancer, CD163 was related to postoperative radiotherapy and poor prognosis, indicating CD163 as a prognostic marker in breast cancer." (PMID 34395626, 2021). "Although studies reported poor prognosis in patients with CD163- expressing cells in breast cancer and rectal cancer; another study reported favorable clinicopathological features in colon cancer." (PMID 33906302, 2021). "According to multiple logistic regression analysis, the CD14+CD16++CD163+ subset was statistically significantly increased in patients with breast cancer." (PMID 35237501, 2021). "Frequently, higher infiltration of TAMs expressing CD163 correlated with unfavorable clinic-pathological features and reduced survival in patients with breast cancer." (PMID 35237501, 2021). "In breast carcinoma, higher infiltration of CD163+ macrophages in the stroma correlated with worse OS, but higher CD163+ TAMs infiltration in tumor invasive front was correlated to an improved prognosis of colorectal carcinoma patients." (PMID 33807310, 2021). "The gene expression of CD163 was upregulated in the breast cancer group with lg2FC = 0.54 and p-adj = 0.036 and correlated with flow cytometry analysis result." (PMID 35237501, 2021).
breast carcinoma (continued). "Pathological evaluations of human mammary cancer tissues revealed that the number of CAFs is positively correlated with the numbers of both CD163+ and CD206+ macrophages." (PMID 34336660, 2021). "Of 108 breast cancer specimens, 66 (61.1%) exhibited high expression of CD163 in the margin (CD163Margin), whereas only 2 (16.7%) specimens of benign breast disease showed high expression." (PMID 33178603, 2020). "There are significant differences in CD163 protein expression in the margin or tumor tissue between 108 breast cancer specimens and 12 controls (p = 0.0015, p = 0.0002, respectively)." (PMID 33178603, 2020). "Here, we showed that the expression of MCT1 and CD163 on macrophages in the infiltration boundary of breast cancer was significantly increased and can be regarded as a useful biomarker for predicting rapid progression." (PMID 33178603, 2020). "Immunohistochemistry staining was utilized to examine the expression level of CD163 in 108 cases of primary breast cancer and 12 cases of benign breast disease." (PMID 33178603, 2020). "We therefore aimed to evaluate the relationships between prediagnostic erythrocyte membrane fatty acids and breast cancer risk by tumor tissue expression of immuno-inflammatory markers (CD4, CD8, CD20, CD163, COX-2) and fatty acid synthase (FAS)." (PMID 32698885, 2020). "We therefore aimed to prospectively investigate the relationships between erythrocyte membrane fatty acid concentrations and subsequent breast cancer risk by tumor tissue expression of several immuno-inflammatory markers (CD4, CD8, CD20, CD163, COX-2) and FAS." (PMID 32698885, 2020). "We demonstrated that the expression of CD163 on macrophages was significantly higher in breast cancer tissues than in normal tissues, especially in the HER2 subtype, although it was not statistically associated with recurrence-free survival (RFS)." (PMID 33178603, 2020). "For this purpose, we performed immunohistochemistry (IHC) staining and immunofluorescence (IF) staining to detect the expression of MCT1 and CD163 in a series of 108 cases of breast cancer." (PMID 33178603, 2020). "A significant correlation existed between MCT1 and CD163 expression in the margin, and high infiltration of MCT1+CD163+ macrophages into the margin predicted rapid progression and poor survival outcomes for breast cancer patients." (PMID 33178603, 2020). "Clinically, in ER-positive and Her2-negative breast cancer, CD163+ TAMs more abundantly infiltrated tamoxifen resistant tissues in comparison with tamoxifen sensitive tissues." (PMID 33194645, 2020). "Taken together, our results successfully demonstrated that the expression of the immune cell subtype-related proteins STAT6, FOXP3, CD8, CD68, and CD163 was different according to the molecular subtype of breast cancer." (PMID 32580398, 2020). "The Si-STAT3 transfection also reduced the percentage of CD206+ or CD163+ THP-1 derived macrophages after the co-culture with linc00514-OVE breast cancer cells." (PMID 32943090, 2020). "CD163 can be an independent macrophage biomarker indicating poor prognosis for breast cancer patients." (PMID 33194645, 2020). "Previous reports have indicated that CD163+ TAMs are most commonly found in triple negative (typically basal subtype) breast cancer and predict poor prognosis." (PMID 32708944, 2020). "Oppositely, the analysis of TAMs in 200 cases of basal-like BC (which is similar to TNBC) showed that increased stromal infiltration of CD68+ or CD163+ macrophages correlated with higher 5-year recurrence and 5-year breast cancer mortality." (PMID 33194645, 2020). "We next investigated the prevalence of M2 TAMs in primary murine mammary tumors from Dek knockout and Dek wild-type animals using CD163 as a marker." (PMID 32708944, 2020). "We retrospectively reviewed the macrophage distribution in 1579 breast cancer specimens with anti-CD68 or anti-CD163 immunohistochemical staining, and further analyzed the overall survival data." (PMID 31528210, 2019).
breast carcinoma (continued). "After 2 days, the expression of CD163 significantly increased in M1 macrophages treated with CMs of either CAFs or MDA-MB-231 breast cancer cells; as a result, resembling the surface expression of M2 macrophages." (PMID 30816272, 2019). "Here, we retrospectively studied the distribution of both CD68+ and CD163+ TAMs in 1579 early stage breast cancer specimens, which currently represents the largest sample size to date." (PMID 31528210, 2019). "The subtype-dependent TAMs abundance was confirmed with microarray expression data showing that the basal-like breast cancer had significantly higher levels of CD163 and CD68 mRNAs compared to luminal breast cancer." (PMID 31406165, 2019). "In breast cancer with adipose stroma, the number of CD163-positive macrophages was greater with stromal ATX positivity (p = 0.003), and the number of CD68-positive and CD163-positive macrophages were greater in cases with stromal LPA3 positivity." (PMID 31035435, 2019). "In fact, our studies with human breast cancer tissue samples also demonstrated that higher number of CAFs is correlated with higher numbers of not only CD163+ but also CD206+ macrophages." (PMID 30816272, 2019). "Stromal ATX positivity (p = 0.010) and stromal LPA3 positivity (p = 0.009) were higher in breast cancer with adipose tissue containing CD163-positive CLS." (PMID 31035435, 2019). "Using the cancer genome atlas database we also found that increased gene expression of Igf-1, Igf-2, and the M2-like macrophage markers cd163 and mrc1 positively correlates with reduced survival in breast cancer patients." (PMID 29367764, 2018). "Although both MMP-9 and CD163 have been traditionally related with M2-phenotype, here we show that they do not always correlate with worse prognosis, as previously reported in breast cancer." (PMID 30558648, 2018). "In this regard, Shabo & Svanvik reported that ~50% of breast cancer cells expressed CD163, and that a third of rectal cancer cells expressed it." (PMID 28957348, 2017). "CD163 expression by breast cancer cells is related to early distant recurrence and reduced survival time." (PMID 28957348, 2017). "Recently, high protein expression of CD163 is observed in oral squamous carcinoma, meningioma, bladder cancer, breast cancer." (PMID 29152078, 2017). "Given the important roles of CD8+ and CD163+ cells in regulating opposing immune circuits, adding an assessment of their differential densities to the prognostic biomarker armamentarium in breast cancer would be valuable." (PMID 28428887, 2017). "They noted expression of CD163 in breast cancer tissues, where it varied significantly and CD163 expression correlated with ER expression." (PMID 28957348, 2017). "M2 macrophages (CD163+) and regulatory T cells (CD25+) in particular are associated with pro-tumor roles during breast cancer progression." (PMID 26964534, 2016). "CD163 expression by breast cancer cells is related to early distant recurrence and reduced survival time, and breast cancer cells expressed CD68." (PMID 26267609, 2015). "They observed aberrant CD163 expression in breast cancers, and created fusions between M2-polarized macrophages and breast cancer cell lines." (PMID 26267609, 2015). "SLN from breast cancer (BC) patients showed an accumulation of CD163+ in sinuses correlated negatively with CD8+ T cells in SLN+." (PMID 26218530, 2015). "We have previously shown that breast cancer TAMs and peripheral blood monocytes from sepsis patients frequently display an increased expression of CD163." (PMID 25992611, 2015). "It was recently shown that breast cancer CD163+ TAMs correlate with Wnt5a expression, the latter factor being responsible for macrophage reprogramming to an anti-inflammatory M2 status." (PMID 26243145, 2015). "Another breast cancer cohort study (n = 144), looking at total macrophage number (CD68+) and M2 macrophages (CD163+) found that CD163 was also associated with other prognostic markers." (PMID 26243145, 2015).